PKNOX1 (PBX/knotted 1 homeobox 1)
Description:
Activates transcription in the presence of PBX1A and HOXA1.
Synonyms: PREP1; pkonx1c
Tractability: PROTAC: ubiquitination databases record sites on it.
Gene: Protein-coding gene on chromosome 21 (42,974,328 to 43,034,475, forward strand). Ensembl gene ENSG00000160199.
Subcellular location: Nucleus
Subcellular location (Human Protein Atlas): Nucleoplasm
Pathways (Reactome):
Developmental Biology: Activation of anterior HOX genes in hindbrain development during early embryogenesis
Gene Ontology:
Molecular function: protein binding; sequence-specific double-stranded DNA binding; DNA-binding transcription factor activity; DNA-binding transcription factor activity, RNA polymerase II-specific; RNA polymerase II cis-regulatory region sequence-specific DNA binding; chromatin binding; DNA binding; sequence-specific DNA binding
Biological process: angiogenesis; positive regulation of transcription by RNA polymerase II; transcription by RNA polymerase II; regulation of DNA-templated transcription
Cellular component: chromatin; cytoplasm; nucleus; transcription regulator complex
Genetic constraint (gnomAD): Loss-of-function variants: 10 observed, 28.51 expected, observed/expected ratio (o/e) 0.35, 90% interval 0.22 to 0.6. The upper end of that interval is the gene's LOEUF score, 0.6, which puts it in group 2 of 6, group 1 being the genes least tolerant of losing a copy. Missense variants: 325 observed, 403 expected, observed/expected ratio (o/e) 0.81, 90% interval 0.74 to 0.88. Synonymous variants: 170 observed, 162.76 expected, observed/expected ratio (o/e) 1.04, 90% interval 0.92 to 1.19.
Homologues: Orthologues: chimpanzee PKNOX1 (100% identical), macaque PKNOX1 (99% identical), mouse Pknox1 (96% identical), guinea pig PKNOX1 (96% identical), rat Pknox1 (96% identical), pig PKNOX1 (94% identical), dog PKNOX1 (88% identical), zebrafish pknox1.2 (71% identical), rabbit PKNOX1 (70% identical), zebrafish pknox1.1 (67% identical), Drosophila melanogaster hth (31% identical), Caenorhabditis elegans unc-62 (30% identical), and 5 more. Paralogues in human: PKNOX2 (62% identical), MEIS2 (35% identical), MEIS1 (34% identical), MEIS3 (32% identical), MEIS3P2 (29% identical), PBX3 (16% identical), PBX1 (16% identical), PBX4 (16% identical), PBX2 (14% identical), TGIF1 (14% identical), TGIF2 (11% identical), TGIF2LX (9% identical), and 1 more.
Diseases named in the same sentence as PKNOX1 in open-access papers:
PKNOX1 is named in the same sentence as 76 diseases in open-access papers, as found by Europe PMC text mining. Sharing a sentence is not in itself a finding about the gene and the disease. The quoted sentences say what the papers report.
diabetes (5 papers, 2017 to 2021). "The aberrant expression of Pknox1 is associated with hepatic glucose and lipid dysmetabolism status of type 2 diabetes mellitus (T2DM) and nonalcoholic fatty liver disease (NAFLD)." (PMID 30338914, 2018). "Prep1/Pknox1 transcription factor has been widely investigated in our previous studies as an important regulator of metabolic homeostasis, as Prep1-deficient mouse model displays better insulin sensitivity and a reduced risk of developing diabetes and diabetes-related comorbidities." (PMID 29349576, 2018).
leukemia (5 papers, 2011 to 2019). A malignant (clonal) hematologic disorder, involving hematopoietic stem cells and characterized by the presence of primitive or atypical myeloid or lymphoid cells in the bone marrow and the blood. "Furthermore, our transcription factor binding motif analysis validated that the HVMRs were enriched for motifs with divergent functions, such as ZNF711 for cognitive disability, PBX3 for leukemia and PKNOX1 for adult spermatogenesis." (PMID 31752687, 2019).
acute myeloid leukemia (4 papers, 2014 to 2025). Acute myeloid leukemia (AML) is a group of neoplasms arising from precursor cells committed to the myeloid cell-line differentiation. "PKNOX1 is mainly “mutated” and “amplified” in tumors, and is concentrated mainly in tumors such as uterine endometrial cancer, acute myeloid leukemia, and gastric adenocarcinoma." (PMID 40625743, 2025).
breast carcinoma (2 papers, 2021 to 2025). "In the Transwell assay, PKNOX1 knockdown significantly reduced the migratory and invasive abilities of breast cancer cells." (PMID 40625743, 2025). "The same results were further validated in breast cancer, another common tumor type.These results provide new evidence of the oncogenic function of PKNOX1 in cancers." (PMID 40625743, 2025). "CCK-8, EdU staining, and colony formation assays were performed to investigate the role of PKNOX1 in breast cancer cell proliferation." (PMID 40625743, 2025). "WB analysis revealed that PKNOX1 was significantly upregulated in five breast cancer cell lines(MCF-7, MDA-MB-453, MDA-MB-231, SK-BR-3, BT-474) compared to the normal mammary epithelial cell line MCF-10A." (PMID 40625743, 2025). "The results revealed that the total protein expression level of PKNOX1 in primary tumor tissues from patients with breast cancer, ovarian cancer, clear cell carcinoma, glioblastoma, and liver cancer was greater than that in adjacent normal tissues." (PMID 40625743, 2025). "We further validated the expression and function of PKNOX1 in breast cancer." (PMID 40625743, 2025). "The results demonstrated that PKNOX1 knockdown significantly suppressed breast cancer cell growth and proliferation compared to the control group.Wound healing and Transwell assays were conducted to examine the role of PKNOX1 in breast cancer cell migration and invasion." (PMID 40625743, 2025). "We need to further explore the specific oncogenic and cancer-promoting molecular mechanisms of PKNOX1 in HCC and breast cancer and even other tumors by combining relevant experiments and multiomics technology." (PMID 40625743, 2025). "In vitro experiments revealed that PKNOX1 is highly expressed in HCC and breast cancer cells and HCC tissues and promotes the growth, proliferation, migration and invasion of HCC and breast cancer cells." (PMID 40625743, 2025). "PKNOX1, and WT1 displayed higher mRNA expression in breast cancer tissues in comparison with normal breast tissues as well as their upregulation was associated with poor OS." (PMID 35186006, 2021). "PKNOX1 is a promising prognostic and immune biomarker in pan-cancer and may play an important role in HCC and breast cancer progression and metastasis." (PMID 40625743, 2025). "In addition, the differential expression and function of PKNOX1 in HCC and breast cancer were explored via Western blotting and proliferation and migration-related experiments." (PMID 40625743, 2025). "Moreover, a series of experiments were performed to reveal, for the first time, the role of PKNOX1 in the occurrence and development of HCC and breast cancer." (PMID 40625743, 2025). "In addition, we conducted a series of experiments to determine the expression level of PKNOX1 in HCC and breast cancer cell lines and tissues, and explored its role in tumor growth, proliferation, migration and invasion in HCC and breast cancer cells." (PMID 40625743, 2025). "Notably, we have only preliminarily explored the carcinogenic ability of PKNOX1 in HCC and breast cancer by combining online analysis databases and experiments." (PMID 40625743, 2025).
Down syndrome (2 papers, 2007 to 2017).
lung carcinoma (2 papers, 2022 to 2025). "Compared with that in adjacent normal tissues, PKNOX1 expression was significantly increased in LIHC, lung cancer, colorectal cancer, and gastric cancer tissues." (PMID 40625743, 2025).
myocardial inflammation (2 papers, 2020 to 2022). "Forced expression of miR-223 activated M1 macrophages toward M2 anti-inflammatory phenotype through targeting PBX/knotted 1 homeobox 1 (PKNOX1), and thus relieving myocardial inflammation." (PMID 32754448, 2020).
breast adenocarcinoma (1 paper, 2021). "PKNOX1 is involved in modulating breast adenocarcinoma progression." (PMID 35186006, 2021).
breast tumors (1 paper, 2012). "Additionally, a number of prosurvival (BCL2, PPEF2) and proapoptosis (BID, HEBP2, and PKNOX1) genes were up- and downregulated, respectively, in bone metastases compared with primary breast tumors." (PMID 23174366, 2012).
colon adenocarcinoma (1 paper, 2025). "The results revealed that in GBMLGG, LGG, LUAD, COAD, COADREAD(Colon adenocarcinoma/Rectum adenocarcinoma Esophageal carcinoma), STES, STAD, BLCA, and ACC, the expression level of PKNOX1 was significantly positively correlated with TMB." (PMID 40625743, 2025).
gastric adenocarcinoma (1 paper, 2025). "This study revealed that the frequency of PKNOX1 gene mutation was highest in patients with gastric adenocarcinoma." (PMID 40625743, 2025). "Previous studies have shown that PKNOX1 can promote the progression of gastric adenocarcinoma by regulating the Hedgehog signalling pathway, and the results are consistent." (PMID 40625743, 2025). "It has been reported that PKNOX1 can promote the progression and metastasis of various tumors, including gastric adenocarcinoma and non-small cell lung cancer." (PMID 40625743, 2025).
Hepatic steatosis (1 paper, 2018). Steatosis is a term used to denote lipid accumulation within hepatocytes. "To further explore the impact of miR‐17‐mediated regulation of Pknox1 on hepatic steatosis, we transfected miR‐17 mimic or Pknox1 siRNA, or co‐transfected miR‐17 mimic with Pknox1 cDNA into HepG2 and L02 cells." (PMID 30338914, 2018).
insomnia (1 paper, 2023). A sleep disorder characterized by difficulty in falling asleep and/or remaining asleep. "In this study, the expression levels of C2CD2L, SPINT2, APOL3, PKNOX1, and A2M exhibited clear associations with most of the 22 immune cells tested, thus suggesting that these genes may participate in the development of insomnia by regulating multiple immune cells." (PMID 38090272, 2023). "qRT-PCR was performed to determine the expression levels of C2CD2L, APOL3, and PKNOX1 in rats with and without insomnia." (PMID 38090272, 2023). "The expression levels of C2CD2L in insomnia samples were significantly lower than those in normal samples, and APOL3 and PKNOX1 showed no significant changes in the two groups." (PMID 38090272, 2023).
Intellectual disability (1 paper, 2026). "Chromosome 21 transcription factors BACH1, PKNOX1 and GABPA emerged as dosage-sensitive hubs regulating genes linked to intellectual disability." (PMID 41545595, 2026).
lipid metabolism disorders (1 paper, 2018). "However, to further determine the therapeutic effectiveness of miR‐17 family‐mediated regulation of Pknox1 in glucose and lipid metabolism disorders, the results from in vitro studies were verified in in vivo studies." (PMID 30338914, 2018).
multiple myeloma (1 paper, 2023). "We analyzed single nucleotide polymorphisms (SNPs) in PKNOX1 (rs2839629) and in the intergenic region between PKNOX1 and CBS (rs915854) by Sanger sequencing in 88 patients with multiple myeloma treated with bortezomib." (PMID 37194045, 2023).
non-alcoholic fatty liver disease (1 paper, 2019). "The transcriptional regulator PKNOX1 is higher in the livers of diabetic and non-alcoholic fatty liver disease patients." (PMID 30987204, 2019).
prostate carcinoma (1 paper, 2020). A carcinoma that arises from epithelial cells of the prostate gland. "Several co-regulators which have been shown to interact with other HOX proteins are expressed in the 22Rv1 prostate cancer cells, including PBX1-3, MEIS1 and MEIS3, and PKNOX1." (PMID 32012197, 2020).
steatosis (1 paper, 2018). Increased lipid within the cytoplasm of cells. "In FFA‐induced hepatocyte steatosis, the hepatic expression level of Pknox1 was inversely correlated with miR‐17 and miR‐20a." (PMID 30338914, 2018). "Overall, these results indicate that miR‐17 and miR‐20a reduce hepatocyte steatosis by targeting Pknox1." (PMID 30338914, 2018). "Furthermore, an inverse correlation was observed between Pknox1 and miR‐17 and miR‐20a in free fatty acids‐induced hepatocyte steatosis." (PMID 30338914, 2018).
testicular germ cell tumor (1 paper, 2025). A germ cell tumor arising from the testis. "In MESO, TGCT(testicular germ cell tumors), LUAD, COAD, COADREAD, STES, STAD, SARC, and LUSC, the expression level of PKNOX1 was significantly positively correlated with MSI, whereas it was significantly negatively correlated with GBMLGG and KIPAN." (PMID 40625743, 2025).
Vestibular schwannoma (1 paper, 2022). A vestibular schwannoma (also known as acoustic neuroma, acoustic neurinoma, or acoustic neurilemoma) is a benign, usually slow-growing tumor that develops from the VIIIth cranial nerve supplying the inner ear. "It is worth noting that through the analysis of Schwann cell transcription factors, we found that Schwann cells may promote the proliferation of vestibular schwannoma by promoting vascular proliferation through transcription factor PKNOX1." (PMID 36304995, 2022).
tumor (12 papers, 2010 to 2025). "The correlations between PKNOX1 expression and the expression of DNA methylation-related genes, immune-related genes, tumor mutation burden (TMB), and microsatellite instability (MSI) were analyzed using Spearman correlation." (PMID 40625743, 2025). "PKNOX1 is significantly highly expressed in most tumor types and is significantly associated with poor patient prognosis and increased clinicopathological stage." (PMID 40625743, 2025). "We evaluated the associations between PKNOX1 expression and clinicopathological features in different tumor types and compared the correlations between clinical T stage and pathological G stage (which assesses the grade of tumor malignancy) and PKNOX1 expression levels." (PMID 40625743, 2025). "We speculate that PKNOX1 may be associated with tumor immunosuppression and immune escape." (PMID 40625743, 2025). "Tumor gene mutations and DNA methylation may explain the abnormal expression of PKNOX1." (PMID 40625743, 2025). "We used the HPA website to further analyse the differential expression of PKNOX1 in tumor tissues and adjacent normal tissues through immunohistochemistry." (PMID 40625743, 2025). "We found that in most tumor types (22 types), PKNOX1 expression levels were positively correlated with the infiltration levels of MDSCs." (PMID 40625743, 2025). "The correlations between PKNOX1 expression in pan-cancer, the tumor immune microenvironment and tumor immunity were investigated." (PMID 40625743, 2025). "The results of this study demonstrated for the first time the expression and clinical significance of PKNOX1 in pan-cancer and its correlation with tumor immunity." (PMID 40625743, 2025). "Recent studies have shown that PKNOX1 dysregulation is closely related to tumor development, metastasis and poor prognosis." (PMID 40625743, 2025). "We need to further explore the regulatory mechanism between PKNOX1 and tumor immunity is needed to confirm this finding." (PMID 40625743, 2025). "The results revealed that PKNOX1 expression levels were significantly positively correlated with the percentage of CNVs in 25 tumor types." (PMID 40625743, 2025). "We extracted the expression data of 37 tumor types from the TCGA database and analysed the relationships between PKNOX1 expression and 60 immune checkpoint-related genes." (PMID 40625743, 2025). "Among these proteins, PKNOX1 is also known to have tumor suppressor function and TGIF1 is reported to act as negative regulator in MLL-rearranged AML36." (PMID 32409701, 2020). "In contrast to oncogenic Meis1, its closely related TALE family member, Pbx-regulating protein 1 (Prep1, aka pKnox1), is a tumor suppressor in mice and humans." (PMID 26259236, 2015). "However, there is currently no pan-cancer evidence from clinical data or in-depth basic research on the relationships between PKNOX1 and various tumor types." (PMID 40625743, 2025). "Moreover, PKNOX1 is closely related to tumor immunity and treatment, and can be used as a biomarker for pan-cancer prognosis and immune efficacy prediction." (PMID 40625743, 2025). "Correlation analysis revealed that PKNOX1 expression levels were significantly negatively correlated with methylation levels in 19 tumor types, indicating that low DNA methylation may be one of the reasons for the high pan-cancer expression of PKNOX1." (PMID 40625743, 2025). "In the future, PKNOX1 could be used as a new target and direction for exploring tumor immunotherapy drugs." (PMID 40625743, 2025). "PKNOX1 may be able to protect tumor cells by inhibiting the body’s immunity and promoting tumor progression and metastasis." (PMID 40625743, 2025). "The expression level and clinical significance of PKNOX1 in most tumor types remain unclear, and its biological role remains to be elucidated." (PMID 40625743, 2025). "Transcription factor PKNOX1 is involved in angiogenesis, suggesting that Schwann cells may promote the proliferation of VS by actively participating in tumor angiogenesis." (PMID 36304995, 2022).
tumor (continued). "In conclusion, PKNOX1 may promote tumor progression and lead to poor prognosis in LIHC." (PMID 40625743, 2025). "There was a significant positive correlation between PKNOX1 expression and YTHDC1 and YTHDF3 expression in 27 tumor types." (PMID 40625743, 2025). "Our previous analysis also revealed that PKNOX1 is highly expressed in HCC and is closely related to poor patient prognosis and tumor immunity." (PMID 40625743, 2025). "KEGG enrichment analysis previously revealed that PKNOX1 is involved mainly in cell-cell adhesion junctions, the cell cycle, and the ERBB, NOTC, and WNT signalling pathways, which affect tumor proliferation, migration, and invasion." (PMID 40625743, 2025). "We constructed the scatter plots of the top five tumor types with positive and negative correlations between immune cells and PKNOX1 expression." (PMID 40625743, 2025). "Our previous pan-cancer analysis revealed that PKNOX1 is highly expressed in HCC and is related to the OS, DSS, and PFI of HCC patients, and that there is a significant correlation between PKNOX1 expression and HCC tumor immunity." (PMID 40625743, 2025). "However, most of these studies are on a single tumor type, and there are currently no clear reports on the expression pattern, prognostic value and biological significance of PKNOX1 in most tumors." (PMID 40625743, 2025). "We speculate that the interaction between PKNOX1 and GMEBA may also promote tumor progression." (PMID 40625743, 2025).